SENP1 (SUMO specific peptidase 1)
Diseases named in the same sentence as SENP1 in open-access papers (continued):
Sharing a sentence is not in itself a finding about the gene and the disease.
tauopathy (1 paper, 2025). Neurodegenerative disorders involving deposition of abnormal tau protein isoforms (tau proteins) in neurons and glial cells in the brain. "DAPK1-mediated SENP1 phosphorylation and degradation promote tau SUMOylation, exacerbating tau pathology and cognitive dysfunction in tauopathy." (PMID 41272902, 2025). "It is worthwhile to validate the pathological relevance of DAPK1/SENP1 axis using transgenic mouse models of tauopathy in the future." (PMID 41272902, 2025). "The influence of DAPK1 on SENP1 expression, tau SUMOylation and phosphorylation was analyzed using a mouse model for tauopathy by overexpressing human tau in the hippocampal CA3 region, as well as using human AD brain tissues." (PMID 41272902, 2025). "First, the lack of specific antibody for SENP1 phosphorylation at Ser126 prevented us from determining SENP1 phosphorylation levels in brains of human AD patients and tauopathy mouse models." (PMID 41272902, 2025).
thyroid cancer (1 paper, 2024). "SENP1 desumoylated HK2 enhanced glycolysis in thyroid cancer, which promoted thyroid cancer proliferation and metastasis." (PMID 38822351, 2024).
vitiligo (1 paper, 2022). Generalized well circumscribed patches of leukoderma that are generally distributed over symmetric body locations and is due to autoimmune destruction of melanocytes. "Notably, markedly decreased SUMOylation of pRb and increased expression of SENP1 were observed in keratinocytes from lesions of vitiligo in comparison with normal keratinocytes, suggesting deSUMOylation of Rb in keratinocytes might play a role in the pathogenesis of vitiligo." (PMID 35650644, 2022).
tumor (59 papers, 2010 to 2026). "We also demonstrated that enhanced SUMOylation of SIRT6 mediated the anti-tumor effects induced by SENP1 deficiency in ESCC cells." (PMID 38954215, 2025). "We found that elevated SENP1 in ESCC tissues was associated with larger tumor size and advanced clinical stage in ESCC patients." (PMID 38954215, 2025). "Imbalance of target protein SUMOylation homeostasis mediated by SENP1 is closely associated with tumor development." (PMID 38389923, 2024). "Existing studies had linked SENP1 to various conditions such as tumours, lung injury and brain injury." (PMID 39205481, 2024). "High expression of SENP1 was significantly associated with histologic grade and tumor lymph node invasion." (PMID 35342335, 2022). "A similar role of SENP1 on tumor growth is also supported by our observation that knockout of SENP1 is linked to decreased HCC cell growth in vitro and in vivo, colony formation, migration and invasion." (PMID 31969492, 2020). "A relevant tumor biological role of SENP1 is also supported by our observation that SENP1 expression was linked to increased cell proliferation." (PMID 26202067, 2015). "The functions of SENP1 and associated genes were primarily complicated in the tumor-related functions and pathways that show SENP1 may mediate the progression and tumorigenesis of cancer." (PMID 34276383, 2021). "Furthermore, statistical analysis was performed to reveal the association between SENP1 expression and tumor characteristics collected from 50 HCC patients." (PMID 31969492, 2020). "Notably, the collected data from TCGA database also proved the upregulation of SENP1 in tumor tissues and the association of high SENP1 expression with lower overall survival rate." (PMID 31969492, 2020). "In this study, we found knockdown of SENP1 inhibits the proliferation of RCC4/VHL cells under hypoxic conditions, and SENP1 expression is positively associated with tumor grade in ccRCC, suggesting it as a potential biomarker for tumor differentiation and aggressiveness." (PMID 27741516, 2016). "Strong SENP1 immunostaining was significantly linked to advanced pathological tumor stage (p < 0.0001), high Gleason grade (p < 0.0001), presence of lymph node metastases (p = 0.0019) and high preoperative PSA-levels (p = 0.0037) when all tumors were jointly analyzed." (PMID 26202067, 2015). "•SENP1 regulates CSC-associated properties in HCC, including OCT4, CD133, PIN1, the EMT, and tumor metastasis." (PMID 41438340, 2026). "SENP1 overexpression disrupts the balance of SUMOylation by targeting specific proteins, significantly contributing to tumor progression and poor prognoses." (PMID 41438340, 2026). "In contrast, SENP1 silencing effectively suppressed tumor progression, as evidenced by the bioluminescence intensity of liver tissues in the GFP-shSENP1 and HBx-shSENP1 groups at 8 weeks post-implantation of HCC cells." (PMID 41438340, 2026). "These clinical observations highlight the potential role of SENP1 in HCC tumor recurrence and metastasis." (PMID 41438340, 2026). "Similar to the effects of OCT4, SENP1 overexpression notably enhanced the formation of secondary tumor spheres, and silencing of SENP1 expression mitigated the enhanced effect." (PMID 41438340, 2026). "SENP1 was selected for further study following our CRISPR/Cas9 screening due to its well-established role in promoting tumor survival and therapy resistance across a variety of cancers." (PMID 39859203, 2025). "One study also showed a correlation between SENP1 expression and the clinicopathological characteristics of tumor patients." (PMID 38954215, 2025). "Taken together, our results declare that the knockdown of SENP1 in ESCC cells slowed down the tumor growth by blocking cell cycle progression and inhibiting cell proliferation without affecting apoptosis." (PMID 38954215, 2025).
tumor (continued). "In this paper, we mainly explore the function and mechanism of SENP1 in tumor cell proliferation, apoptosis, invasion, metastasis, stemness, angiogenesis, metabolism and drug resistance." (PMID 38389923, 2024). "AnxA6 deSUMOylation contributes to HCC progression and EMT phenotype, and the combination of AnxA6 and SENP1 is a better tumor biomarker for diagnosis of HCC grade malignancy and prognosis." (PMID 38566133, 2024). "Deeply exploring the specific regulatory mechanism of SENP1 in tumor invasion and metastasis is helpful to limit tumor progression." (PMID 38389923, 2024). "And in vivo, triptolide decreases the weight and volume of xenograft tumors, which indicates that Triptolide has potent anti-tumor effect through suppressing SENP1." (PMID 38389923, 2024). "In summary, these results illustrate that SENP1 promotes tumor cell proliferation through various mechanisms." (PMID 38389923, 2024). "The expression of SENP1 in breast primary tumor tissues was significantly higher than that in normal tissues." (PMID 38389923, 2024). "Studies in neuroblastoma demonstrated that SENP1 silence suppressed tumor invasion and metastasis via downregulating MMP2 and MMP9 levels." (PMID 38389923, 2024). "Immunohistochemical results showed that the subcutaneous tumor proliferation marker KI67 decreased after SENP1 was silenced." (PMID 38822351, 2024). "This is the first time to develop small molecule SENP1 inhibitors as radiosensitizers, which is of great significance for its application in tumor radiotherapy." (PMID 38389923, 2024). "SENP1 plays a crucial role in tumor progression and is expected to be a critical target for cancer therapy." (PMID 38389923, 2024). "SENP1 high expression represents larger tumor volume, deeper invasion extent, later pathological stage, and distant metastasis." (PMID 38389923, 2024). "In the hypoxic microenvironment of the EOC, SENP1 alleviates tumor cells’ sensitivity to chemotherapy via deSUMOylating HIF-1α and upregulating its expression." (PMID 37415251, 2023). "Wang reported that the plasma exosome SENP1 levels were related to tumor size, tumor location, necrosis rate, pulmonary metastasis, and surgical stage." (PMID 37377390, 2023). "It has been reported that SENP1 expression is elevated in several cancers and provides pro-tumor functions." (PMID 36284084, 2022). "It is also reported that SENP1 inhibits tumor development via regulation of myeloid-derived suppressor cell (MDSC), which is important in immune suppression." (PMID 35342335, 2022). "Serial histological sections confirmed the presence of a significantly higher number of metastatic tumor foci in the SENP1 overexpressing group." (PMID 36284084, 2022). "Triptolide shows anti-tumor activity on PC that involves downregulation of SENP1, restoration of SUMOylation/de-SUMOylation balance, and negative regulation of ARs and c-Jun expression." (PMID 35465332, 2022). "More importantly, in this study we found that high expression of SENP1 in TNBC tumors was significantly related to tumor lymph node metastasis and correlated with a short OS and RFS in TNBC patients." (PMID 35342335, 2022). "As a summary, our study suggests that high expression of SENP1 in TNBC samples promotes TNBC tumor development and leads to poor prognosis." (PMID 35342335, 2022). "Histological analysis of the tumor boundaries showed that implanted SENP1-overexpressing ccRCC cells showed invasion of tumor cells under the mouse kidney capsules, which was undetectable in tumors derived from the control cells." (PMID 36284084, 2022). "According to IHC staining in 146 TNBCs, SENP1 is significantly higher expressed in tumor tissues compared with adjacent normal tissues (P < 0.001)." (PMID 35342335, 2022). "We showed that SENP1 expression was higher in TNBC tumor tissues and related to TNBC prognosis, supporting SENP1 as an independent risk factor." (PMID 35342335, 2022).
tumor (continued). "We conducted co-IP using transplanted tumor tissues and found that in the SENP1 down-regulated group, GATA1 binding affinity with SUMO1 was increased and GATA1 SUMOylation was enhanced as well." (PMID 35342335, 2022). "The expression of SENP1 obtained from plasma exosomes of OS patients was closely related to the tumor size, tumor location, necrosis rate, lung metastasis, and surgical staging." (PMID 36211364, 2022). "A significantly deregulated SENP1 expression was demonstrated in tumor specimens of the SENP1 knockdown group compared with control tumor specimens." (PMID 34312374, 2021). "The results of IHC indicated that compared with paired NCTs, 56.9% (58/102) of tumor tissues showed increased SENP1 expression." (PMID 33686713, 2021). "The findings of this study indicate the important role of SENP1 in carcinogenesis and supply a potential relationship and a mechanism between SENP1 and tumor-immune interactions." (PMID 34276383, 2021). "At first, we explored genetic alterations of SENP1 in the 33 tumors, including 10,969 tumor samples." (PMID 34276383, 2021). "Plasma exosome-derived SENP1 levels were related to tumor size, tumor location, necrosis rate, pulmonary metastasis, and surgical stage." (PMID 33791211, 2021). "We stained the tissue microarray with HK2 and SENP1 antibodies and scored the staining on a scale of 0–3 based on the percentage of immunoreactive tumor cells and the staining intensity." (PMID 33753739, 2021). "For this purpose, we considered SENP1 with activated interactions in the tumor state as potential drug targets." (PMID 34276383, 2021). "This study found that SENP1 expression was increased in NSCLC tumor tissues than adjacent tissues in patients with surgical NSCLC receiving adjuvant chemotherapy." (PMID 35782332, 2021). "Meanwhile, SENP1 IHC score was higher in the tumor tissue than in the adjacent tissue (n = 157) (p < 0.001); SENP1 mRNA expression in the tumor tissue was also elevated than that in the adjacent tissue (n = 102) (p < 0.001)." (PMID 35782332, 2021). "The plasma exosome-derived SENP1 levels were related to tumor size, tumor location, depth of tumor invasion, lymph node metastasis, and TNM stage." (PMID 34422639, 2021). "SENP1 IHC score and SENP1 mRNA expression were increased in tumor tissue than adjacent tissue (p < 0.001)." (PMID 35782332, 2021). "Tumor growth rate was calculated by the equation of [tumor volume at day 21 - tumor volume at day 0]/21, and it was lower in the SENP1 knockdown group than in the control group." (PMID 34312374, 2021). "Elevated SENP1 IHC score was correlated with > 5 cm tumor size (p = 0.045), the occurrence of lymph node metastasis (p = 0.003), and more advanced TNM stage (p = 0.012)." (PMID 35782332, 2021). "Data of the TCGA shown higher expression of SENP1 in tumor tissues of CHOL, DLBC, ESCA, GBM, PAAD, and THYM than normal tissues, but lower expression of SENP1 in tumor tissues than normal tissues in TGCT (p-value < 0.01)." (PMID 34276383, 2021). "For example, one study suggests that SENP1 expression in tumor is negatively correlated with treatment response in patients with NSCLC; another study reports that SENP1 is a potential predictive factor for chemosensitivity in patients with NSCLC." (PMID 35782332, 2021). "The expression of SENP1 protein was assessed in the tumor tissue and paired adjacent tissue by IHC assay." (PMID 35782332, 2021). "In this study, we found that SENP1-Sirt3 signalling promoted T cell infiltration into tumour tissue and enhanced anti-tumour immunity." (PMID 34272364, 2021). "Accordingly, the final tumor size and weight in SENP1-KO group was significantly reduced compared with the negative control." (PMID 31969492, 2020). "The expression level of SENP1 was obviously higher in tumor tissues than para-carcinoma tissues in the randomly selected clinical specimens." (PMID 31969492, 2020).
tumor (continued). "Taken together, these results strongly proved that SENP1 promotes tumor development and progression of HCC." (PMID 31969492, 2020). "Knockout of SENP1 resulted in impaired growth, migration and invasion, and enhanced apoptosis in vitro, as well as inhibition of tumor growth in vivo." (PMID 31969492, 2020). "In order to verify the effects of SENP1 knockout on tumor growth in vivo, tumor-bearing mice model was constructed by injection of HepG2-SENP1-KO cells The trend of tumor growth showed significant slowdown in the SENP1-KO group than the negative control." (PMID 31969492, 2020). "The immunohistochemical staining of both tumor and para-carcinoma tissues with SENP1 antibody showed similar results, indicating the upregulated expression of SENP1 in tumor tissues and suggesting the involvement of SENP1 in HCC progression." (PMID 31969492, 2020). "The roles of the CLDN6/SENP1/HIF-1α signaling on tumor metastasis were evaluated by function experiments and clinical samples." (PMID 32093760, 2020). "The fact that the prevention of SUMOylation of UBE2T (K8R mutation) has similar effect on properties of HepG2 cells with SENP1 suggests the deSUMOylation as the mechanism of SENP1 to induce UBE2T then the tumor progression." (PMID 31969492, 2020). "Some reports have shown that SENP1 stabilizes hypoxia inducible factor 1 (HIF-1α) to promote tumor growth and metastasis, and increases vascular endothelial growth factor (VEGF) expression to increase angiogenesis in the tumors." (PMID 28417919, 2017). "We believe SENP1 silencing leads to the increased SMAD4 levels due to improved stability of SMAD4 in the tumor cells." (PMID 28417919, 2017). "We now show that tumor suppressive PTEN signaling is induced in SENP1-Tg to enhance prostate epithelial cell apoptosis." (PMID 27852060, 2017). "Here, by integrated gene expression and metabolomic analyses of 36 matched pairs of tumor and adjacent normal tissues, we showed that expression of Sentrin/SUMO-specific protease 1 (SENP1) is positively associated with glycolysis levels in ccRCC." (PMID 27741516, 2016). "We quantified SENP1 mRNA in the 36 pairs of ccRCC tumors (T) and adjacent normal tissues (N), and divided the tumor samples into SENP1 high-expression and low-expression groups according to the log2 value of the ratio of T/N SENP1 mRNA level for each pair." (PMID 27741516, 2016). "We found SENP1 expression positively correlated with tumor grade (P < 0.01); patients with higher tumor grade also showed higher SENP1 expression than those with low tumor grade." (PMID 27741516, 2016). "Because of the strong link between SENP1 expression and PTEN deletion, we extended the analyses to tumor subgroups stratified according to the SENP1/ PTEN status." (PMID 26202067, 2015). "Here we evaluated the diagnostic value of measuring the urinary content of hTERT, MCM5, PPP1CA, and SENP1 mRNAs for detection of tumor recurrence." (PMID 21106093, 2010). "Furthermore, in vivo experiments using an orthotopic xenograft model revealed a significant reduction in tumor metastasis following SENP1-knockdown." (PMID 41438340, 2026). "SENP1 could serve as a novel biomarker of early tumor recurrence and metastasis, especially for HBV-related HCC." (PMID 41438340, 2026). "Our findings revealed that both elevated and reduced expression levels of UBC9, SENP1, SENP3, SENP5, and SENP7 may be associated with poor prognosis across various tumor types." (PMID 41268439, 2025). "Moreover, H&E and immunohistochemical analysis revealed that the density of Ki67-positive tumor cells was significantly higher in Senp1 flox/flox mice compared to cKO mice." (PMID 38954215, 2025). "Furthermore, patients with high expression of SENP1 exhibited a shorter overall survival period, implying that SENP1 promotes tumor progression." (PMID 38954215, 2025). "SENP1 has been reported to promote tumor invasion and metastasis in various cancers." (PMID 38389923, 2024).